Y_RNA (Y RNA )
Gene: Miscellaneous RNA gene on chromosome 15 (69,406,441 to 69,406,552, forward strand). Ensembl gene ENSG00000207395.
Homologues: Orthologues: chimpanzee Y_RNA (100% identical), macaque Y_RNA (96% identical). Paralogues in human: RNY1P5 (89% identical), Y_RNA (88% identical), Y_RNA (87% identical), Y_RNA (86% identical), Y_RNA (85% identical), Y_RNA (84% identical), RNY1 (83% identical), Y_RNA (83% identical), RNY1P7 (82% identical), Y_RNA (82% identical), RNY1P6 (81% identical), Y_RNA (81% identical), and 97 more.